NFIB (nuclear factor I B)
Diseases named in the same sentence as NFIB in open-access papers (continued):
Sharing a sentence is not in itself a finding about the gene and the disease.
small cell lung carcinoma (23 papers, 2015 to 2026). Small cell lung cancer (SCLC) is a highly aggressive malignant neoplasm, accounting for 10-15% of lung cancer cases, characterized byrapid growth, and early metastasis. "Perhaps more relevantly, NFIB has also been implicated in regulating the adhesion of epithelial cancers including small cell lung cancer (SCLC)." (PMID 35954220, 2022). "employed a small cell lung cancer (SCLC) mouse model to investigate the crucial role of CARM1 methylation of NFIB in its transformational activity." (PMID 39964832, 2025). "Some examples are NFIB and NFIX’s role in super-enhancer maintenance of hair follicle stem cells, NFIB’s prometastatic actions in small cell lung cancer, and the recent identification of NFIB as a genome organizer in the prereplication complex." (PMID 39617063, 2025). "Previous studies have also shown that NFIB can increase chromatin accessibility in small-cell lung cancer (SCLC) cells and stem cells." (PMID 37037903, 2024). "NFIB was reported as an oncogene that promotes metastasis of small cell lung cancer (SCLC) by increasing the chromatin accessibility in gene distal regions." (PMID 36690626, 2023). "Among the NFI proteins, NFIB is ubiquitously expressed in human tissues and frequently overexpressed/amplified in various types of cancer, such as small cell lung cancer, melanoma, and ER− breast cancer." (PMID 37604829, 2023). "Here the authors show that protein arginine methyltransferase, CARM1, methylates transcription factor NFIB to promote the growth of small cell lung cancers." (PMID 36690626, 2023). "Deregulation of other NFI family members has been reported in several tumor types: NFIB is overexpressed in metastatic neuroendocrine lung tumors and it drives metastatic progression of small cell lung cancers by increasing chromatin accessibility." (PMID 37353485, 2023). "This study found that NFIB promotes metastasis of human small cell lung cancer (SCLC) cells through a widespread increase in chromatin accessibility." (PMID 36569748, 2022). "A previous study revealed that NFIB promoted pro-metastatic neuronal gene expression by stabilizing chromatin accessibility in small cell lung cancer cells." (PMID 31754405, 2019). "Increased copy number and expression of NFIB has been reported for small cell lung cancer, prostate cancer and triple negative breast cancer consistent with an oncogenic role in these cancers." (PMID 27083054, 2016). "In small cell lung carcinomas NFIB regulates cell viability and proliferation and it is considered an oncogene." (PMID 25763778, 2015). "Importantly, NFIB harbors both oncogenic and metastatic activities, and is often overexpressed in small cell lung cancer (SCLC)." (PMID 36690626, 2023). "This increase in NFIB expression is puzzling in that NFIB was recently identified as a new oncogene in small cell lung cancer and most particularly in triple negative breast cancer (TNBC), where it contributes to cell proliferation/survival through a direct suppression of p21 transcription." (PMID 31847118, 2019). "For example, NFIB inactivation was shown to contribute to osteosarcoma progression and cutaneous carcinogenesis, while other studies demonstrates that NFIB may acts as an oncogene in small cell lung cancer." (PMID 27533466, 2016). "In models of liver metastasis from small cell lung carcinoma, copy amplification of NFIB (Nuclear factor I B) produced genome-wide accessibility increases." (PMID 39095874, 2024). "Additionally, the “ErbB Signaling Pathway,” “Tight Junction,” “Glioma,” and “Small Cell Lung Cancer” pathways are also prominently represented, further highlighting the broad regulatory impact of NFIA, NFIB, NFIC, and NFIX on several types of cancer." (PMID 39617063, 2025).
glioma (16 papers, 2016 to 2025). A benign or malignant brain and spinal cord tumor that arises from glial cells (astrocytes, oligodendrocytes, ependymal cells). "More recently, Chen and colleagues demonstrated that mice with loss of function NFIB mutant alleles developed more gliomas and have shortened survival time." (PMID 35655758, 2022). "Only one study reported the effect of NFIB in carcinogenesis, where NFIB deficiency exacerbated the development of high-grade glioma." (PMID 35655758, 2022). "Increased expression of NIFA or NFIB is associated with increased survival in patients with high-grade gliomas." (PMID 34012965, 2021). "Loss of 9p, which also includes the tumour suppressor CDKN2A besides NFIB, has been implicated directly in glioma progression." (PMID 27083054, 2016). "miR-346 inhibited the growth of glioma cells by targeting NFIB and may be a new prognostic and diagnostic biomarker for glioma." (PMID 31807116, 2019). "Because NFIB is rarely mutated in glioma and at least one copy of the gene is present in over 95% of GBM, we investigated whether NFIB expression could be increased by drug treatment of GBM cells." (PMID 27083054, 2016). "This hypothesis is supported by a genome-wide study of genetic alterations associated with grade II and III gliomas revealing loss of heterozygosity of NFIB with increasing glioma grade." (PMID 27083054, 2016). "In addition to glioma, NFIB has been linked with several other cancers, in either an oncogenic or tumour suppressive context." (PMID 27083054, 2016). "Recent evidence has shown that NFIB gene expression is involved in the development of various types of tumors such as breast cancers, adenoid cystic carcinoma, and glioma." (PMID 31807116, 2019). "Lentivirus transfection, real-time PCR, western blotting, immunohistochemistry, cell proliferation assays, and mouse experiments were used to examine the relationship between miR-346 and its regulation of NFIB in glioma cells." (PMID 31807116, 2019). "In this study, we focused on the effect of miR-346 on glioma cell growth and its tentative relationship with NFIB." (PMID 31807116, 2019). "In particular, miR-346 is shown to inhibit glioma proliferation by targeting nuclear factor I B (NFIB) and may become a potential prognostic and therapeutic candidate." (PMID 36226036, 2022). "Moreover, ectopic expression of NFIA or NFIB in a glioma xenograft model is sufficient to promote differentiation of tumor cells." (PMID 34012965, 2021). "Roles for NFIA and NFIB as tumor suppressors in glioma have been documented, and expression of these two factors is inversely correlated with tumor grade such that higher grade tumors are associated with lower expression of NFIA or NFIB." (PMID 34012965, 2021). "For example, NFIB inhibits the growth of glioma cells, and its low expression may be an important reason for the occurrence of glioma." (PMID 34194482, 2021). "NFIB appeared in all four databases and has been reported as a target gene of miR-346 in glioma." (PMID 33061846, 2020). "miR-346 suppressed the growth of glioma cells by directly targeting NFIB." (PMID 31807116, 2019). "NFIB overexpression promoted the proliferation and colony-forming efficiency of glioma cells." (PMID 31807116, 2019). "Therefore, miR-346 inhibited the proliferation of glioma cells by targeting NFIB in vitro, which was confirmed in vivo by animal experiments showing that overexpression of miR-346 inhibited tumorigenesis." (PMID 31807116, 2019). "Furthermore, using the independent French dataset, we found that the significant survival benefit associated with higher expression of NFIB existed for patients with GBM, astrocytoma and glioma." (PMID 27083054, 2016). "In addition, using the independent Rembrandt glioma dataset, we found that improved patient survival was also evident when NFIB gene copy number was considered independently of gene expression." (PMID 27083054, 2016). "Like NFIB, NFIA and NFIX also have been implicated in glioma." (PMID 27083054, 2016).
glioma (continued). "Our observation that NFIB expression decreases with increasing glioma grade, together with the demonstration of its tumour-suppressive effects in GBM, suggest that NFIB loss may be a contributory factor in glioma progression." (PMID 27083054, 2016). "In addition, more experiments are needed to determine the function of NFIB in glioma." (PMID 31807116, 2019). "Moreover, overexpression of NFIB suppressed miR-346-regulated growth of human glioma cells." (PMID 31807116, 2019). "The markers for this population are largely expressed only in glioma cells (e.g., NFIB, MAP1B, TUBB2B) and they express low levels or have no expression of myeloid/immune markers (CD74, APOE, HLA genes, and CD45)." (PMID 40588233, 2025). "Thus, expression of NFIB is a prognostic factor that predicts improved survival for GBM, astrocytoma and glioma." (PMID 27083054, 2016). "Interestingly, the oncogenic effect of NFIB in neural GBM is akin to the action of NFIA in maintaining the glial progenitor cell pool in the embryonic spinal cord and perhaps analogously promotes the propagation of the glioma stem cell compartment in this subtype." (PMID 27083054, 2016).
colorectal cancer (13 papers, 2010 to 2025). A primary or metastatic malignant neoplasm that affects the colon or rectum. "In colorectal cancer, melanoma, and gastric cancers, overexpression of NFIB was associated with epithelial-mesenchymal transition (EMT), migration and invasion." (PMID 34922631, 2021). "Nuclear factor I B promotes colorectal cancer cell proliferation in vitro and growth in vivo by increasing intracellular NAD+ levels through downregulation of the NAMPT-targeting micro-RNA, miR-182-5p." (PMID 37491379, 2023). "Our previous study found that NFIB can promote colorectal cancer (CRC) cell proliferation in acidic environments." (PMID 37491379, 2023). "Another study suggested that miR-138-5p is a vital regulator of chemoresistance in colorectal cancer cells by acting on the NFIB-Snail1 axis." (PMID 36568230, 2022). "For instance, LINC00461 was shown to strengthen the colorectal cancer cells' proliferation and invasion ability by miRNA-323b-3p/NFIB Axis." (PMID 34966465, 2021). "miR-138-5p targeted NFIB, and regulated Snail1 expression, which mediated colorectal cancer cell migration and chemotherapy resistance." (PMID 33013202, 2020). "We used qRT-PCR to investigate the expression of miR-138-5p, Snail1, NFIB in colorectal cancer cells." (PMID 33013202, 2020). "NFIB mRNA and Snail1 mRNA expression were in positive correlation in 100 colorectal cancer tissues (p < 0.001)." (PMID 33013202, 2020). "Among them, NFIB, which was predicted with a high score and is upregulated in human colorectal cancer as a well-known oncogene, was confirmed as the most likely gene directly targeted by miR-346." (PMID 33061846, 2020). "Altogether, our study unvailed that miR-138-5p targeted the NFIB-Snail1 axis to inhibit migration and chemoresistance of colorectal cancer cells." (PMID 33013202, 2020). "Another study demonstrated that by targeting the NFIB-Snail1 pathway, miR-138-5p might critically regulate the migratory potential and resistance of colorectal cancer cells to chemotherapy." (PMID 39596660, 2024). "However, the role of NFIB in NAD+ salvage biosynthesis in colorectal cancer remains to be elucidated." (PMID 37491379, 2023). "In addition, LINC00461 possesses an oncogenic role in colorectal cancer cells by targeting microRNA (miR)-323b-3p in the nuclear factor I B (NFIB) signaling pathway." (PMID 33869744, 2021). "Expression of NFIA and NFIB was downregulated in colorectal cancer according to the TCGA database." (PMID 32219034, 2020). "Our research indicates that miR-138-5p could be a crucial modulator controlling colorectal cancer cell migration and chemoresistance, by acting upon the NFIB-Snail1 axis." (PMID 33013202, 2020). "Through targeting NFIB-Snail1 axis miR-138-5p could regulate colorectal cancer cell migration andchemoresistance." (PMID 33013202, 2020). "Expression of NFIA, NFIB and NIFC was reduced in colorectal cancer tissues evaluated based on mRNA HiSeq expression data from the TCGA database." (PMID 32219034, 2020). "For colorectal cancer, analysis using the Oncomine database revealed significant difference only in NFIA and NFIB mRNA levels between tumor and normal samples." (PMID 32219034, 2020). "Similar effects have been shown for NFIB in gastric cancers, TNBC, SCLC, and colorectal cancer." (PMID 34922631, 2021).
melanoma (12 papers, 2017 to 2022). A malignant, usually aggressive tumor composed of atypical, neoplastic melanocytes. "The epigenetic modulator EZH2 was also investigated as it has recently been linked to melanoma invasion and metastasis, and has been previously identified as a target of NFIB in neuronal cell lineages." (PMID 28119061, 2017). "Most recently NFIB has been shown to mediate a highly invasive and migratory phenotype in melanoma, where it directly promotes EZH2 expression, also leading to changes in the chromatin state of tumor cells to facilitate this aggressive behavior." (PMID 35655758, 2022). "Among BRN2 target genes, it was shown that NFIB can mediate BRN2-driven melanoma invasion through dynamic changes in the chromatin state of melanoma cells." (PMID 35406721, 2022). "Although NFIB has an established role as an oncogene in nonsmall cell lung cancer and melanoma, it has also been reported that NFIB has a tumor suppressor function in some cancer types." (PMID 33981484, 2021). "Previous studies showed that NFIB governs epithelial‐melanocyte stem cell behaviour and facilitates melanoma cell migration and invasion." (PMID 33751828, 2021). "In melanoma, specifically, NFIB-targeted upregulation of EZH2 led to the epigenetic silencing of MITF, promoting a highly invasive phenotype." (PMID 34922631, 2021). "ChIP-ChIP experiments have detected BRN2 binding at the NFIB locus in vivo using 501 Mel human melanoma cells." (PMID 28119061, 2017). "Accordingly the EZH2 inhibitor GSK343 was used to assess the contribution of EZH2 to NFIB driven melanoma cell migration in the A2058− NFIB and MM96L− NFIB cells." (PMID 28119061, 2017). "Together our data reveal that NFIB has the ability to promote dynamic changes in the chromatin state of melanoma cells to facilitate migration, invasion and metastasis." (PMID 28119061, 2017). "Our data suggests that increased melanoma cell migration in response to elevated NFIB is in part achieved through EZH2 mediated down-regulation of MITF expression." (PMID 28119061, 2017). "In silico analysis of RNA-Seq data from 471 melanoma tumours contained in the TCGA database revealed a strong correlation between NFIB expression levels and an invasive gene signature." (PMID 28119061, 2017). "Protein analysis of these melanoma cell models prior to injection confirms that MITF has been drastically reduced in these NFIB lines." (PMID 28119061, 2017). "We were able to demonstrate that EZH2 is up-regulated following both BRN2 and NFIB stable overexpression in melanoma cells." (PMID 28119061, 2017). "The effect of BRN2, MITF and NFIB over-expression in melanoma cell invasiveness was then determined using spheroids embedded in a collagen matrix, with invasion monitored at 24 h time points over a 72 h period." (PMID 28119061, 2017). "Interestingly, lung metastases also had greater relative NFIB expression when compared with the subcutaneous tumours, suggesting that NFIB expression is increased in more aggressive melanomas." (PMID 28119061, 2017). "This analysis revealed enrichment of BRN2 binding within the first intron of the NFIB gene locus, further suggesting that BRN2 may be able to directly bind NFIB and regulate its expression in melanoma cells." (PMID 28119061, 2017). "NFIB expression was found to be significantly higher in four of the six lines (2.8–3.5 fold) with considerably lower expression seen in the MM418c5 and A11 melanoma lines." (PMID 28119061, 2017). "Modulation of NFIB expression induced a very similar migration phenotype to BRN2 whereby a significantly increased migratory capacity was seen in response to over-expression of NFIB within wound healing assays, while siRNA knock-down significantly decreased melanoma cell migration rates." (PMID 28119061, 2017).
melanoma (continued). "Here we report the regulation of expression of the NFIB transcription factor by BRN2 in melanoma cells, which in turn acts to increase cell migration and potentially invasion through the positive and negative regulation of the epigenetic regulator EZH2 and MITF respectively." (PMID 28119061, 2017). "Moreover, our analysis of NFIB function in melanoma cells, together with recent evidence of NFIB as a powerful driver of SCLC metastasis suggest that NFIB may play a broader role in metastatic spread of other cancers." (PMID 28119061, 2017). "At the core of these critical contributors to tumor aggressiveness lies NFIB, a downstream target of c-Myc (SCLC) and an inducer of EZH2 (melanoma)." (PMID 34922631, 2021). "An oncogenic role for NFIB has been shown in triple-negative breast cancer (TNBC), small cell lung cancer (SCLC), colorectal and gastric cancers, and melanoma by enhancing tumor growth, epithelial-mesenchymal transition (EMT), migration, and invasion." (PMID 34922631, 2021). "Together this data suggests a relationship between NFIB and BRN2 expression in melanoma cells at both the protein and transcript levels." (PMID 28119061, 2017). "A2058 human melanoma cells engineered to over-express either BRN2 or MITF were analyzed by qRT-PCR for expression of all four members of the NFI gene family, NFIA, NFIB, NFIC and NFIX." (PMID 28119061, 2017). "Potential co-localisation of NFIB and BRN2 in vivo was initially examined in xenograft tumours generated in BALB/c Foxn1nu mice using the A2058, MM96L, and HT144 human melanoma cell lines." (PMID 28119061, 2017). "Accordingly, we chose to examine the expression and function of NFIB in the context of BRN2 function in primary melanocytic cells and melanoma cells to determine if this transcription factor plays a role in BRN2 mediated phenotype switching." (PMID 28119061, 2017). "In addition, studies have shown that NFIB directly promotes EZH2 expression and mediates highly invasive and migratory phenotypes in melanoma." (PMID 33981484, 2021). "Conversely, constitutive BRN2 overexpression was also performed in these same cell lines and revealed a commensurate increase in both NFIB (3.8, 3.7, 2.4 fold respectively) and EZH2 (2.5, 2.3, 2.6 fold respectively) expression across all three melanoma cell lines." (PMID 28119061, 2017). "While melanoma cells often behave differently within the tumour microenvironment compared to cultured cells, it is possible that BRN2 and NFIB regulate additional genes that counteract the growth phenotype that might be anticipated with high EZH2 expression." (PMID 28119061, 2017).